ZNF852 (zinc finger protein 852)
Description:
May be involved in transcriptional regulation.
Tractability: PROTAC: ubiquitination databases record sites on it.
Gene: Protein-coding gene on chromosome 3 (44,491,766 to 44,510,636, reverse strand). Ensembl gene ENSG00000178917.
Subcellular location: Nucleus
Subcellular location (Human Protein Atlas): Cytosol
Gene Ontology:
Molecular function: DNA-binding transcription factor activity, RNA polymerase II-specific; RNA polymerase II cis-regulatory region sequence-specific DNA binding
Biological process: regulation of transcription by RNA polymerase II; regulation of DNA-templated transcription
Cellular component: nucleus
Genetic constraint (gnomAD): Loss-of-function variants: 31 observed, 41.51 expected, observed/expected ratio (o/e) 0.75, 90% interval 0.56 to 1.01. The upper end of that interval is the gene's LOEUF score, 1.01, which puts it in group 4 of 6, group 1 being the genes least tolerant of losing a copy. Missense variants: 561 observed, 606.89 expected, observed/expected ratio (o/e) 0.92, 90% interval 0.86 to 0.99. Synonymous variants: 186 observed, 209.43 expected, observed/expected ratio (o/e) 0.89, 90% interval 0.79 to 1.
Homologues: Orthologues: chimpanzee ZNF852 (93% identical), macaque ZNF852 (88% identical), pig ZNF852 (74% identical). Paralogues in human: ZKSCAN7 (91% identical), ZNF287 (45% identical), ZNF527 (44% identical), ZNF214 (41% identical), ZNF572 (41% identical), ZNF34 (41% identical), ZNF285 (40% identical), ZNF17 (40% identical), ZNF530 (38% identical), ZNF416 (38% identical), ZNF774 (37% identical), ZNF136 (37% identical), and 38 more.
Diseases named in the same sentence as ZNF852 in open-access papers:
ZNF852 is named in the same sentence as 1 disease in open-access papers, as found by Europe PMC text mining. Sharing a sentence is not in itself a finding about the gene and the disease. The quoted sentences say what the papers report.
tumor (1 paper, 2023). "Moreover, when the ZNF852 is knocked down using the CRISPR/cas9 system in GC, its ability to reproduce is inhibited, along with the decreased expression of Nanog, SRY-box 2 (Sox2) and Oct4, meaning that ZNF852 preserves the self-renewal and tumor stem cell properties of GC." (PMID 37174714, 2023).